AHR (aryl hydrocarbon receptor)
Diseases named in the same sentence as AHR in open-access papers (continued):
Sharing a sentence is not in itself a finding about the gene and the disease.
prostate carcinoma (continued). "Agonist of AhR increased CYP1B expression, mostly in PBMCs from patients with prostate cancer." (PMID 39850551, 2024). "PARP7 expression in primary prostate cancer tumors is correlated with both AHR and AR, which is not surprising given the TIPARP gene is a direct target of both transcription factors." (PMID 37077937, 2023). "On the basis of our cell data, exploiting the AHR pathway and RBN2397 treatment might provide a PARP7-based strategy for inhibiting advanced prostate cancer." (PMID 37077937, 2023). "Therefore, AhR competed with HIF-1α for binding with ARNT and impaired the formation of the prostate cancer by suppression of the production of VEGF." (PMID 37830596, 2023). "The AR degradation process through AhR activation was not identified in all types of prostate cancer cells." (PMID 36613955, 2022). "The Cignal XRE and ARE luciferase reporter assays were utilized to determine the activity of AhR and AR signaling pathways in androgen independent (C4-2) prostate cancer cells in the presence and absence of inhibitors." (PMID 28671964, 2017). "The assay showed that C4-2 prostate cancer cells have a high level of AhR and AR promoter activity in the absence of inhibitor treatment." (PMID 28671964, 2017). "Our results show that TCDD exposure does not result in AhR degradation in the castration resistant C4-2 prostate cancer cells." (PMID 26154658, 2015). "The data presented here, reveals that AhR can modulate proliferation of prostate cancer cells in the absence of androgen receptor." (PMID 24755659, 2014). "This current study reveals AhR’s ability to modulate growth of prostate cancer cells independent of androgen receptor activity." (PMID 24755659, 2014). "Chemical ablation of AhR signaling can reduce the growth of advanced prostate cancer cells, an effect not achieved with androgen receptor inhibitors or growth in androgen depleted media." (PMID 24755659, 2014). "Although several studies have shown the effects of AhR ligand activation in prostate cancer cell lines, no study has investigated the role of constitutive AhR signaling on prostate cancer cellular growth." (PMID 24755659, 2014). "In our study, knocking down the AhR per se in LNCaP cells did not alter prostate cancer cell growth, suggesting that the basal levels of AhR do not exert an inhibitory effect unless stimulated by ligand." (PMID 20140206, 2010). "Therefore, our findings reveal a critical role for TDO2-Kyn-AhR signalling in ADT-induced tumour dormancy and recurrence in prostate cancer and suggest a new therapeutic target for androgen-sensitive prostate cancer by combining ADT with targeting the TDO2-Kyn-AhR pathway." (PMID 40759641, 2025). "Tryptophan metabolism was one of the 27 pathways, and the downstream target genes of AhR, CYP1A1 and CYP1B1, were considerably elevated after AhR binding, suggesting that tryptophan metabolism is significantly activated in recurrent castration-resistant prostate cancer." (PMID 40759641, 2025). "One study indicated that the effects of BaP in prostate cancer might be mainly due to its AhR-mediated activity rather than the activation of the DNA damage response." (PMID 38410974, 2024). "Despite the studies confirming AhR ligand regulation of AR signaling, AhR may possess intrinsic functions that regulate growth of prostate cancers independent of AR status that has not been fully studied." (PMID 24755659, 2014). "Hence, cross-talk between AHR and inflammation-mediated pathways, but not CD84-mediated pathways, in monocytes but not macrophages may contribute to the modulation of tumor environments by I3C and DIM in prostate cancer." (PMID 29364159, 2018).
Arthritis (42 papers, 2014 to 2025). Inflammation of a joint. "In this study, Breg cell differentiation favored pro-inflammatory response and reduced IL-10 expression, thus exacerbating arthritis in AhR-deficient mice." (PMID 39478858, 2024). "In AhR-deficient mice, IL-10-producing Breg and regulatory T (Treg) cells are substantially reduced, and arthritis is exacerbated." (PMID 37256149, 2023). "In vivo, B cell-specific deletion of AhR caused exacerbated arthritis and promoted excessive inflammation by depleting B10." (PMID 35359922, 2022). "B cell AhR-deficient mice develop exacerbated arthritis, show significant reductions in IL-10-producing Bregs and regulatory T cells, and show an increase in T helper (Th) 1 and Th17 cells compared with B cell AhR-sufficient mice." (PMID 31722204, 2019). "In vivo, B cell-specific deletion of AhR caused exacerbated arthritis, reduced IL-10 production by CD19+CD21hiCD24hiBregs, and reduced the frequency of Foxp3+Tregs and expansion of Th1 and Th17 cells." (PMID 31722204, 2019). "We also used mice genetically deficient for AHR (Ahr KO) and IL-17Ra (Il17ra KO) to determine the in vivo mechanism of smoking-induced arthritis aggravation." (PMID 29884199, 2018). "Activation of AHR increases Th17 differentiation in vitro and Ahr genetic-deficient mice develop less severe collagen-induced arthritis via modulation of Th17." (PMID 29884199, 2018). "They showed that mice with AhR deficiency in Bregs develop exacerbated arthritis, associated with significant reductions in IL-10-producing Bregs as well Tregs, and show an increase in Th1 and Th17 cell subsets compared with mice, which have AhR-sufficient Bregs." (PMID 34576041, 2021). "Transgenic mice carrying human SE-coding alleles, when exposed to AhR agonists, showed a robust increase in arthritis severity, bone destruction, overabundance of osteoclasts, and IL17-expressing cells in the inflamed joints and draining lymph nodes of arthritic mice." (PMID 33066667, 2020). "This loss of AHR specifically in T cells suppressed collagen-induced arthritis development." (PMID 30574142, 2018). "Our study not only corroborates the previous findings of an AhR cell autonomous role in CD4 T cells for arthritis development, but identify that the major environmental risk for RA development, cigarette smoking, induces disease aggravation through an AhR-dependent increase in Th17 cell response." (PMID 29884199, 2018). "AhR deficiency has been shown to ameliorate collagen-induced arthritis." (PMID 25615839, 2015). "However, views on the role of AhR in RA pathogenesis are controversial, with some studies supporting the potential of AhR activation to alleviate arthritis, while others suggesting that elevated AhR expression in RA patients is associated with greater disease severity." (PMID 40181974, 2025). "In antigen-induced arthritis (AIA) mice, supplementation with SCFA decreased arthritis severity and supported regulatory B cell differentiation via the aryl-hydrocarbon receptor (AhR)." (PMID 40794325, 2025). "Microbiota-derived metabolites suppress arthritis by amplifying AhR activation in regulatory B Cells." (PMID 39880074, 2025). "Animal studies have found that smoking leads to increased arthritis and Th17 cells, and that these alternations are dependent on the transcription factor aryl hydrocarbon receptor (AHR)." (PMID 38068867, 2023). "Further, AhR-dependent IL-10 Breg induction in B cells inhibits GC and plasmablast differentiation and regulates arthritis." (PMID 37256149, 2023). "Tetrandrine, as a potential ligand of AhR, can activate AHR and regulate the Th17/Treg balance to inhibit osteoclastogenesis and improve arthritis in CIA rats." (PMID 35979373, 2022). "NOR promoted the differentiation and function of Treg cells in intestinal tissue of CIA mice (in an AhR-dependent manner) by activating AhR, and thus played an anti-arthritis role." (PMID 35979373, 2022).
Arthritis (continued). "The aryl hydrocarbon receptor (AHR) controls several inflammatory and metabolic pathways involved in various diseases, including the development of arthritis." (PMID 33734594, 2021). "Our data clearly show the HQ influence over the synoviocyte activation, cytokine secretion and oxidative stress, and confirm the involvement of AhR and IL-17R on the exacerbated experimental arthritis in vivo." (PMID 34200499, 2021). "Here, we determine that 5-HT’s main metabolite 5-HIAA upregulates AhR-dependent gene transcription and ll10 transcription in B cells and is immunoregulatory in arthritis." (PMID 32213346, 2020). "Under these conditions, WT and AhR−/− B cells are exposed to identical inflammatory signals following arthritis induction." (PMID 32213346, 2020). "For example, TCDD and other toxic compounds contained in cigarette smoke acted as AhR agonists, induced Th17 cells, and exacerbated the disease in a mouse experimental model of arthritis." (PMID 32899743, 2020). "Researchers have reported that sinomenine induces the generation of intestinal Tregs and attenuates arthritis via activation of the AhR even in CIA." (PMID 32232043, 2020). "AHR activation links the expansion of Th17 cells and the production of IL-17A, which is a pro-inflammatory cytokine that aggravates arthritis." (PMID 32218599, 2020). "To confirm a role for AhR in the immune-modulatory effect of butyrate supplementation on the B cell compartment and arthritis severity, we took advantage of Ahrfl/−Mb1cre/+ mice, which have a B cell specific deletion of AhR." (PMID 32213346, 2020). "In a very recent study, butyrate (a short-chain fatty acid) supplementation reduced experimental arthritis severity via an increase in 5-hydroxyindole-3-acetic acid, a Trp metabolite derived from serotonin and agonist of AhR." (PMID 32899743, 2020). "Helping to understand the mechanisms underlying RA, osteoarthritis (OA) and osteoporosis (OP) is the finding that the effects of AHR activation are potentiated by Human Leucocyte Antigen-DRB1, a significant risk factor for the development of arthritis." (PMID 32194572, 2020). "Isoquinoline alkaloids found in plants have been shown to have AHR activity and induce Tregs alleviating collagen-induced arthritis." (PMID 30574142, 2018). "Our data demonstrate that the disease-exacerbating effects of cigarette smoking are AHR dependent and environmental pollutants with AHR agonist activity can induce arthritis aggravation by directly enhancing Th17 cell development." (PMID 29884199, 2018). "Mice null for IL-17 or AHR were protected from cigarette-smoking induced arthritis and exposure to PAHs aggravated arthritis suggesting that AHR ligands in cigarette smoke drive Th17 responses in vivo." (PMID 30574142, 2018). "Data presented here demonstrate that cigarette smoking-induced aggravation of arthritis is dependent on the activation of AHR and the subsequent induction of Th17 and production of IL-17A." (PMID 29884199, 2018). "In this study, we investigated the role of AHR activation in the aggravation of experiment arthritis induced by exposure to cigarette smoke." (PMID 29884199, 2018). "This study shows that smoking-induced arthritis aggravation is dependent on AhR activation in Th17 cells and IL-17Ra signaling." (PMID 29884199, 2018). "Experimental studies have found that smoking can worsen arthritis and increase the proportion of Th17 cells, indicating that AHR activation may be an important mechanism by which smoking influences arthritis progression." (PMID 40405982, 2025). "Furthermore, butyrate reduced arthritis severity by increasing the levels of AhR ligands, i.e., serotonin-derived metabolite 5-hydroxyindole-3-acetic acid, where AhR activation supported regulatory B cell function." (PMID 36830830, 2023). "In addition, butyrate was already shown to reduce arthritis severity via the stimulation of AhR in IL-10-producing regulatory B cells." (PMID 38046818, 2023).
Arthritis (continued). "B cell-specific deletion of AhR in mice exacerbated arthritis, diminished IL-10 production by Bregs cells, and reduced the frequency of Tregs cells and expansion of inflammatory Th1 and Th17 cells compared with B cell AhR-sufficient mice." (PMID 36779190, 2023). "Intriguingly, similar effects (protection against arthritis) could be noticed in Ahr KO animals and upon AHR activation with the VAG539 agonist." (PMID 33734594, 2021). "Also, our data suggest that the activation of the AhR/IL-17 pathway is closely involved in the worsening of experimental arthritis in HQ-exposed mice." (PMID 34200499, 2021). "Finally, conditional Ahr depletion of Rorc‐expressing cells was sufficient to attenuate arthritis, thereby uncovering a previously unsuspected role of AHR in type 3 innate lymphoid cells during acute arthritis." (PMID 33734594, 2021). "Herein, we aimed to investigate the involvement of AhR and IL-17 in the mechanism of action in the worsened HQ-related arthritis and evaluate the outcome of RA human fibroblast-like synoviocytes (RAHFLS) exposed to HQ, associated or not with the activation of the TNF-α pathway." (PMID 34200499, 2021). "We first noted an increased expression of the Ahr gene in the synovium 24h after serum injection before the appearance of clinical signs of arthritis, which likely accounts for increased expression of known AHR‐dependent target genes expression such as Il‐22 and Cyp1a1." (PMID 33734594, 2021). "To investigate whether there was an AhR-independent mechanism in the Breg-mediated regulation of arthritis by butyrate supplementation, we performed a four-way comparison analysis among all the groups." (PMID 32213346, 2020). "Furthermore, the effects of cigarette smoking on inducing arthritis aggravation are AhR dependent, and environmental pollutants with AhR agonist activity exacerbate arthritis by directly enhancing Th17 cell differentiation." (PMID 31772949, 2019). "Having confirmed the contribution of AhR in the programming of the IL-10+CD19+CD21hiCD24hiBreg transcriptional profile, we explored the impact of AhR deficiency specifically in B cells on the immune response associated with arthritis." (PMID 31722204, 2019). "We hypothesized that AHR activation by cigarette smoke components could be responsible for the aggravation of arthritis." (PMID 29884199, 2018). "In our experiments, a brief exposure to cigarette smoke and AhR activation can induce aggravation of arthritis, while in humans the timeline for duration of cigarette smoke exposure and RA development might be longer." (PMID 29884199, 2018). "Using this model, we identified that smoking-induced arthritis aggravation is dependent on AHR activation in T cells, Th17 expansion, and interleukin 17 receptor A (IL-17RA) signaling, showing a strong link between this pollutant receptor and arthritis progression." (PMID 29884199, 2018). "Thus, butyrate supplementation may control a molecular program by activating the AhR, supporting Breg function while inhibiting the development of arthritis." (PMID 40264032, 2025). "Finally, VAG539 injections in K/BxN‐treated Il‐22 deficient mice did not improve arthritis symptoms, demonstrating that IL‐22 production is required downstream of AHR activation to promote protective effects." (PMID 33734594, 2021). "Also, we showed here that the HQ exposure did not exacerbate the arthritis symptomatology in AhR- or IL-17R-KO mice, associating the AhR and IL-17 pathway with the HQ actions." (PMID 34200499, 2021). "This, taken together with previous findings demonstrating that AhR suppresses plasmablast differentiation, led us to hypothesize that butyrate supplementation suppresses arthritis and alters B cell subset composition either directly or indirectly by activation of AhR in B cells." (PMID 32213346, 2020).
Arthritis (continued). "Similarly, AhR deficiency restricted to B cells impairs IL-10+CD19+CD21hiCD24hiBreg differentiation and function, resulting in an increase of IFNγ and IL-17-expressing CD4+ T cells, a decrease in Tregs, and the development of an exacerbated arthritis." (PMID 31722204, 2019). "Similarly, tetrandrine, an alkaloid constituent, alleviated severity of arthritis, reduced serum levels of pro-inflammatory cytokines, and restored the Th17/Treg balance via the AHR, measured by serum levels of IL-17 and IL-10 respectively in collagen-induced arthritis mice." (PMID 30574142, 2018). "Moreover, although other cell types (e.g. ILC3 and γδ T cells) are also sources of IL-17 during inflammatory process, our data from adoptive transfer experiments suggest that CD4 T cells are the main target responsible for arthritis aggravation induced by AhR activation." (PMID 29884199, 2018). "Moreover, the AhR antagonist CH223191 also reduced smoking-induced arthritis aggravation, suggesting blockage of this receptor could be an important target for RA management." (PMID 29884199, 2018). "The exacerbation of symptoms in models of arthritis such as CIA and antigen-induced arthritis (AIA) is prevented by deletion of either AHRs or of IL-17 receptors supporting the view that AHR activation can drive Th17 differentiation." (PMID 32194572, 2020). "For examples, Norisoboldine, a natural aryl hydrocarbon receptor agonist, promotes TREG differentiation and inhibits collagen-induced arthritis through regulating the balance between TREG and TH17 cells." (PMID 31664129, 2019). "Consistent with this notion, smoking-induced arthritis aggravation and increase in Th17 frequencies in AIA was markedly inhibited when the mice were treated with an AHR antagonist, CH223191." (PMID 29884199, 2018). "Additionally, a former study demonstrated that intestinal microbiota-derived butyrate activated AhR, a functional transcriptional marker of CD19+CD21+CD24+ Breg cells, in a Breg cell-dependent manner, which inhibited arthritis and reduced arthritis severity." (PMID 39478858, 2024). "AHR, CAV1, CRP, CXCL2, IRF1, SPP1 and other targets play important roles in the pathogenesis of arthritis and can be used as key targets for the treatment of arthritis." (PMID 37637408, 2023). "Therefore, ADRB2, AHR, CRP, IRF1, PTGS1, SPP1 and other targets can be used as potential targets for CC in the treatment of arthritis, and it is of great significance to explore its role of CC in the treatment of arthritis." (PMID 37637408, 2023). "Nevertheless, butyrate no suppresses arthritis severity in Ahrfl/-Mb1cre/+, which has a B cell-specific deletion of AhR." (PMID 36779190, 2023). "Furthermore, administration of both the AHR agonist VAG53927 enhancing IL‐22, and rIL‐22 attenuated serum transfer arthritis." (PMID 33734594, 2021). "In our experiments, the role of AhR on smoking-induced arthritis aggravation is demonstrated by the lack of smoking effects on mice genetically deficient to AhR." (PMID 29884199, 2018). "Similar to what was observed for AIA mice exposed to cigarette smoke, the AHR agonist FICZ failed to induce arthritis aggravation of AIA in Il17ra−/− mice." (PMID 29884199, 2018). "Butyrate supplementation suppresses arthritis in a Breg-dependent manner by increasing the level of the serotonin-derived metabolite 5-Hydroxyindole-3-acetic acid (5-HIAA), which activates the aryl-hydrocarbon receptor (AhR), a newly discovered transcriptional marker for Breg function." (PMID 32213346, 2020). "Indeed, Ahr KO mice were protected from cigarette smoke-induced arthritis aggravation and did not display increase in TH17 frequencies, suggesting that AHR activation is an important mechanism for cigarette smoke effects on arthritis." (PMID 29884199, 2018).
Arthritis (continued). "Tetrandrine can enhance the ubiquitination and degradation of spleen tyrosine kinase (Syk) through AhR/non-receptor tyrosine kinase/c-Cbl signaling pathway and regulate the expression of Syk and phospholipase-Cγ, thereby inhibiting osteoclastogenesis and bone destruction in arthritis." (PMID 35979373, 2022). "This is consistent with an earlier report showing that AHR in CD4 T cells, but not in other immune cells, is important for arthritis development and Th17 expansion." (PMID 29884199, 2018). "Similarly to WT mice, butyrate supplementation suppressed arthritis severity and CD4+IL-17+T cell frequency only in AhR-sufficient Mb1cre/+ mice but not in Ahrfl/−Mb1cre/+ mice." (PMID 32213346, 2020).